IQCJ (IQ motif containing J)
Tractability: No criterion of Open Targets' tractability assessment is met for any kind of drug.
Gene: Protein-coding gene on chromosome 3 (158,962,928 to 159,266,307, forward strand). Ensembl gene ENSG00000214216.
Genetic constraint (gnomAD): Loss-of-function variants: 9 observed, 11.88 expected, observed/expected ratio (o/e) 0.76, 90% interval 0.46 to 1.32. The upper end of that interval is the gene's LOEUF score, 1.32, which puts it in group 5 of 6, group 1 being the genes least tolerant of losing a copy. Missense variants: 129 observed, 116.74 expected, observed/expected ratio (o/e) 1.11, 90% interval 0.96 to 1.28. Synonymous variants: 46 observed, 46.27 expected, observed/expected ratio (o/e) 0.99, 90% interval 0.78 to 1.27.
Homologues: Orthologues: chimpanzee IQCJ (88% identical), rabbit IQCJ (82% identical), mouse Iqcj (80% identical), pig IQCJ (80% identical), rat Iqcj (79% identical).
Diseases named in the same sentence as IQCJ in open-access papers:
IQCJ is named in the same sentence as 5 diseases in open-access papers, as found by Europe PMC text mining. Sharing a sentence is not in itself a finding about the gene and the disease. The quoted sentences say what the papers report.
endothelial dysfunction (1 paper, 2022). In vascular diseases, endothelial dysfunction is a systemic pathological state of the endothelium (the inner lining of blood vessels) and can be broadly defined as an imbalance between vasodilating and vasoconstricting substances produced by (or acting on) the endothelium. "IQCJ-SCHIP1 and GIMAP8 can be suggested as a novel genes requiring further investigation in the context of genotoxic stress induced endothelial dysfunction." (PMID 36140167, 2022).
cancer (3 papers, 2019 to 2025). A tumor composed of atypical neoplastic, often pleomorphic cells that invade other tissues. "In addition to these, we also identified some novel genes among the 14-CpG markers that were not previously associated with cancer recurrences such as IFFO1, ALKAL1, FAHD1, FSTL4, SLC7A9, IQCJ-SCHIP1, CLDN11 and three other CpGs at intergenic regions." (PMID 34207933, 2021).
IQCJ also shares sentences with these, for which no sentence is quoted: breast carcinoma (1 paper); diabetes (1); ovarian carcinoma (1).